SDC1 (syndecan 1)
Diseases named in the same sentence as SDC1 in open-access papers (continued):
Sharing a sentence is not in itself a finding about the gene and the disease.
tumor (continued). "The proportion of patients with positive expression of SDC1 in tumor cells was higher than those patients in PNMDC (p = 0.003)." (PMID 37069585, 2023). "Heparinase stimulates syndecan-1 expression, cleavage and shedding to promote fibrillar collagen deposition and tumor growth." (PMID 36906534, 2023). "Before obvious formation of distant metastasis, systemic dissemination of quiescent tumor cells has been existed depending on normal ECM-cell adhesion-induced syndecan-1 activation." (PMID 36906534, 2023). "Heparinase can also degrade perlecan and syndecan-1 (Sdc-1/CD138) to mediate tumor cell growth and invasion." (PMID 36906534, 2023). "In contrast, IGF1R activation in tumor cells is strictly dependent on Sdc1, even if IGF1 is present, and is therefore blocked by SSTNIGF1R." (PMID 36968227, 2023). "The expression and immunoregulatory function of SDC1 in cancers are tumor-specific and their details remain controversial." (PMID 37069585, 2023). "Nevertheless, cell-type-specific effects of Sdc-1 on the TF pathway cannot be excluded, and these have partially been observed in a previous study with a focus on Sdc-1-dependent tumor angiogenesis." (PMID 36980251, 2023). "Combinatorial targeting of syndecan-1 and B-fibronectin with these reagents resulted in a synergistic effect and more efficient inhibition of tumor growth in vivo in a mouse model." (PMID 37370735, 2023). "There is evidence that heparanase and SDC1 work together to promote diverse signaling pathways both in tumor cells and in surrounding microenvironmental cells, such as endothelial and immune cells." (PMID 36980680, 2023). "The same study suggested that the membranous localization of SDC1 retards tumor growth while its cytoplasmic expression supports tumor progression." (PMID 36980680, 2023). "It should be noted that, in addition to MM cells, the MM1 scFv-Fc antibody also bound tumor epithelial cells known to overexpress syndecan-1, although the binding was 2–4-fold lower than that of MM cells." (PMID 37046595, 2023). "Syndecan-1 (CD138) is also expressed on the surface of MM cells and when shed, it promotes tumor growth and metastasis." (PMID 37958838, 2023). "There are tumors in which syndecan-1 protects against cancer and others, such as myeloma and mammary and lung cancer, in which it promotes tumor progression." (PMID 38139365, 2023). "COL1A2, COL1A1, COL6A3, and SDC1 were expressed at higher levels in tumor tissue compared with normal tissue in the TCGA-BC, TCGA-CRC, and TCGA-ESCA datasets." (PMID 38002057, 2023). "In our TNBC cohort, we found that the expression of SDC1 was significantly higher in tumor cells than in PNMDCs." (PMID 37069585, 2023). "Based on the expression and biological localization analyses of L/R pairs, we identified two L/R pairs (LAMB3/CD44 and ANGPTL4/SDC1) with high reliability between tumor cells and PCs." (PMID 37138324, 2023). "MK-expressing tumor cells are found to interact with 7 known receptors, including SDC1, SDC4, PTPRZ1, LRP-1, and the integrin family (ITGA4-ITGB1 and ITGA6-ITGB1) as well as NCL." (PMID 37835544, 2023). "Changes in syndecan-1 expression are associated with attenuated biosynthesis of Osteoprotegerin and osteoclast formation, identifying tumor-derived syndecan-1 as a novel positive regulator of osteoclastogenesis and a new player in the tumor–bone dialog." (PMID 36555315, 2022). "This suggests that the soluble form of Sdc-1 has an important role in proliferation, but its role is tumor type-dependent." (PMID 35155241, 2022). "It was demonstrated that, interacting with focal adhesions, Sdc-1 modulates regeneration of the tumor cell cytoskeleton in a rho-GTPase-dependent manner." (PMID 35155241, 2022). "SDC1, a heparin cell surface proteoglycan that functions as a growth factors and chemokines co-receptor, which strongly correlated to the tumor aggressiveness and clinical results." (PMID 35037689, 2022).
tumor (continued). "On one hand, it has been observed that the cervix exhibits a differential expression of Sdc-1 depending on the type of cell and epithelium as well as, in non-neoplastic and neoplastic lesions and the histological grade of the tumor." (PMID 35155241, 2022). "For example, in CRC, the Syndecan-1 pathway, a host pathway that modulates tumour growth and progression, is correlated with microbial taxa such as Parvimonas and Bacteroides fragilis that are known to promote intestinal carcinogenesis." (PMID 35577971, 2022). "We studied if the presence or overexpression of syndecan-1 the major transmembrane heparan sulfate proteoglycan of the liver can interfere with the tumor-induced upregulation of SPOCK1." (PMID 35186754, 2022). "The GBM samples with clinic characteristics were selected to find the gene sets not only related to SDC1 but also tumor immune infiltration." (PMID 35669186, 2022). "Again, the effect of Sdc-1 on apoptosis seems to be dependent on the type of tumor but also on its membrane localisation." (PMID 35155241, 2022). "The effect seems to be related to tumor aggressiveness because cells of well-differentiated tumors can rescue their cell surface syndecan-1." (PMID 35186754, 2022). "SDC1 can promote the formation of specific tumor microenvironments by altering the packaging of miRNAs and circRNAs by exosomes." (PMID 36358833, 2022). "We were able to find high syndecan-1 cell clusters within primary tumors (N = 4) and tumor-bearing livers (N = 6), while analyzed control livers (N = 4) did not present similar clusters." (PMID 34349175, 2021). "At the same time, the LFA-1-mediated invasion of NK and cytotoxic T cells is suppressed by the Sdc1 shed into the tumor microenvironment, providing a protected environment for growth of the tumor." (PMID 34778093, 2021). "The results showed that CACNA1H, IL13RA1, NUP43, PGK1, and SDC1 were highly expressed in tumor samples, while expression of AK3 was significantly decreased." (PMID 34600547, 2021). "Diffuse WGA staining in tumor cell clusters is accompanied by marked cytoplasmic redistribution of E-cadherin, β-actin and syndecan-1 and by marked changes in cell morphology from polygonal to elongated." (PMID 34572115, 2021). "Together, the results from the A549 and the B6FS tumor cell models indicated that nuclear SDC1 plays a role in regulating epithelial-mesenchymal plasticity in human tumor cells." (PMID 34208075, 2021). "Shed SDC-1, along with factors that bind to its HS chains, facilitates establishment of a tumor microenvironment that promotes disease recurrence and robust growth via the enhancement of growth factor signaling in host cells." (PMID 35118073, 2021). "First, syndecan-1 expression on tumor cells using immunohistochemistry is on a continuous spectrum, whereas in our evaluation, categorical and metrical variables need to be defined." (PMID 34206469, 2021). "An integral component of the extracellular matrix, the type 1 transmembrane glycoprotein syndecan-1 (SDC-1) binds cytokines and growth factors involved in tumor microenvironment modulation." (PMID 35118073, 2021). "SDC1 abnormal expression, for example, is determinant in tumour cell growth, invasion and migration in different types of cancer, such as colorectal, gallbladder and oesophageal carcinomas." (PMID 33494442, 2021). "In non-tumor tissues, Sdc1, Sdc2, Sdc3, Sdc4, and Sdcbp were expressed in all four prostate lobes, with no significant quantitative difference among them." (PMID 34445387, 2021). "The secreted GAG and CD44 ligand hyaluronic acid (HA), and the cell surface PG syndecan-1 (Sdc-1) modulate the expression and activity of cytokines, chemokines, growth factors, and adhesion molecules, acting as critical regulators of tumor cell behavior." (PMID 34070901, 2021). "Shed Sdc1 is present in high levels in many tumour cell types where it shuttles growth factors to the nucleus by altering histone acetylation in host cells." (PMID 33922532, 2021).
tumor (continued). "The results demonstrate that nuclear translocation contributes to the capacity of SDC1 to regulate epithelial-mesenchymal plasticity in human tumor cells and opens up to mechanistic studies to elucidate the mechanisms involved." (PMID 34208075, 2021). "The results provide new insight into the mechanisms by which SDC1 plays a role in EMT and tumor progression and open up further studies to explore the mechanisms by which nuclear SDC1 regulates the EMT machinery in tumor cells." (PMID 34208075, 2021). "The overwhelming majority of the data apply to syndecan-1, and it is important to recognize that while many studies are correlative, there are now direct data implicating syndecan-1 with tumor aggressiveness." (PMID 33921767, 2021). "The Kruskal-Wallis test showed a significant difference in the percentage and intensity of syndecan-1 expression in tumor cells among the evaluated lesions (p = 0.009 and p < 0.001 respectively)." (PMID 31540870, 2021). "In light of our present study findings, these data emphasize the potential therapeutic benefit of targeting cell-autonomous and tumor microenvironmental Sdc-1 against tumor angiogenesis of TNBC, which is worth exploring in future translational studies." (PMID 34066023, 2021). "Nuclear translocation of SDC1 was shown to regulate tumour signalling by shuttling growth factors to the nucleus and by altering histone acetylation." (PMID 33494442, 2021). "It is noteworthy that IBC tumor overexpress the heparan sulfate proteoglycan syndecan-1, aligning with KEGG pathway analysis, including proteoglycans in cancer." (PMID 33901254, 2021). "Since in many cases, the presence of stromal syndecan-1 is a sign of tumor aggressiveness, it appears likely that shed syndecan-1 is a mediator of invasion, proliferation and permissive alterations in the tumor microenvironment." (PMID 33921767, 2021). "All (100%) of the 30 pleomorphic adenomas showed expression of syndecan-1 in tumor cells and the staining was localized to the cytoplasmic and membranous components of ductal and non-ductal neoplastic cells." (PMID 31540870, 2021). "Similar to Sdc-1 mode of action, spliced F3 binds to the endothelial cell integrin αvβ3 and α6β1 to evoke tumor angiogenesis via protein tyrosine kinase-2 signaling." (PMID 34066023, 2021). "Nuclear translocation of SDC-1 further enhances its modulation of the EMT as well as tumor invasiveness." (PMID 35118073, 2021). "Shed SDC-1 has recently been reported to undergo nuclear translocation in both tumor and bone marrow stromal cells, with the presence of HS chains required for this process." (PMID 35118073, 2021). "Degradation of nuclear Sdc-1 by heparanase enhances histone acetyltransferase activity and promotes expression of genes that aggressively drive the attainment of a tumour phenotype." (PMID 33922532, 2021). "In this study, we report that re-localization of syndecan-1 from the cell surface to the nucleus contributes to its capacity to regulate the identity switch in tumor cells." (PMID 34208075, 2021). "Sdc-1 has an influence on a myriad of biological processes, relevant to tumor progression; however, the role of cell-autonomous Sdc-1 expression in TNBC cells on in vitro angiogenesis has not been explored." (PMID 34066023, 2021). "Pathologic SDC-1 expression interferes with complex molecular signals and impact tumor grade, invasiveness and prognosis." (PMID 35118073, 2021). "Regulating the HS chains of syndecan-1 has been suggested to promote malignancy in premalignant tumor epithelial cells through regulation of FGF binding activity." (PMID 34068954, 2021). "Based on our results, it will be interesting to elucidate the more specific role of nuclear SDC1 for the regulation of EMT in tumor cells." (PMID 34208075, 2021). "Expression of oncogenic K-Ras led to upregulation of syndecan-1 on the surface of tumor cells, in a process mediated by MEK." (PMID 33921767, 2021).
tumor (continued). "To unveil possible mechanisms related to Mn effect on tumor cell migration, we analyzed the expression pattern of the migration-related molecules β1-integrin and syndecan-1, as well as F-actin, in wound healing assays." (PMID 34349175, 2021). "Colocalization of FGF2 in the nucleus and FGFR1 in the perinuclear region of mesenchymal tumor cells is dependent on co-translocation of syndecan-1." (PMID 34068954, 2021). "In the Pten mouse, the number of RPKM for Sdc1 was compatible with increased expression across stages of tumor progression, in PIN lesions, and at medium and advanced stages." (PMID 34445387, 2021). "Here, we analyzed the function of the cell surface molecule Syndecan-1 in tumor angiogenesis in a 3D cell culture system." (PMID 34066023, 2021). "A rather general observation is that in the complex relationship between the stroma and the tumor cells syndecan-1 acts as a mediator of reciprocal interactions." (PMID 32388727, 2020). "Previously, independent studies in various tumor types examined the potential influences of SDC1 on the efficacy of different chemotherapeutic agents." (PMID 33114033, 2020). "In order to reconfirm this result, we overexpress ANPEP protein and examined its effects in protein expressions of ANPEP/SDC1/integrin β4 axis and xenograft tumor growth." (PMID 32756007, 2020). "One study showed that syndecan-1 was critical for tumor presence and growth, serving as a KRAS activator, and this suggested that it was a potential therapeutic target in PDAC treatment." (PMID 32825245, 2020). "Increasing evidence indicates that human tumor cells are capable of inducing stromal syndecan-1 expression which represents a distinct subgroup with worse life expectancy." (PMID 32388727, 2020). "Data in different tumor entities have revealed further pathogenetic mechanisms for the functional interplay of Sdc-1 and HPSE." (PMID 32477959, 2020). "This tumor-induced aberrant stromal syndecan-1 expression is an unfavorable prognostic factor in mammary and gastric malignancies, in head and neck squamous cell cancers as well as other tumors." (PMID 32388727, 2020). "Higher syndecan-1 levels, in turn, accelerate the proliferation of the tumor cells, thus constituting a positive feedback loop." (PMID 32388727, 2020). "Several studies examined the impact of syndecan-1 in various neoplasms and concluded that its altered expression often led to malignant neoplasms." (PMID 32983743, 2020). "Shedding of syndecan-1 has also been particularly studied in the context of cancer and has been shown to promote tumor cell proliferation and migration in vitro and tumor growth in vivo." (PMID 32937952, 2020). "In a previous study, we demonstrated that the upregulation of SDC1 hampers cell proliferation and that the localization of SDC1 is important for the fate of tumor cells." (PMID 32664515, 2020). "Previous studies on the role of syndecan-1 in tumors mainly focused on the changes of this HSPG taking place on the surface of tumor cells." (PMID 32388727, 2020). "As even NFs started to express syndecan-1 in direct co-culture indicates that tumor cells are responsible for the induction of this proteoglycan." (PMID 32388727, 2020). "The question has to be addressed if syndecan-1 expression promotes the aggressive phenotype of EMT transformed tumor cells present in the stroma." (PMID 32388727, 2020). "In comparison with the normal epithelium, tumor cell membrane syndecan-1 immunoreaction was moderately or strongly decreased in the majority of the cases; moreover, its occasional disappearance was also observed." (PMID 32388727, 2020). "Downregulation of syndecan-1 expression in P3 xenografts resulted in decreased tumor size and tumor angiogenesis." (PMID 32847060, 2020).
tumor (continued). "Given that HPSE has multiple functions in the tumor microenvironment it is conceivable that SST0001 decreases the invasion of Sdc-1 depleted cells through HPSE-mediated signaling events, or via direct inhibition of its basement-membrane degrading properties." (PMID 32477959, 2020). "Syndecan-1 is a cell surface heparan sulfate proteoglycan and its expression has been shown to be correlated with tumor cell differentiation in various cancers." (PMID 31967990, 2020). "According to the SDC1 staining intensity and the extent of positive tumor cells, our data showed that SDC1 was expressed at low levels in 29.4% (140/477) of CRCs, moderately expressed in 44.8% (228/477) of CRCs, and highly expressed in 22.8% (109/477) of CRCs." (PMID 31182980, 2019). "Our results revealed that tumor Sdc-1 silencing promotes the proportion of Th1 (IFN-γ+CD4+) subset of non-IBC patients when stimulated with the secretome of Sdc-1-silenced SUM-149 cells but not in direct co-culture, as compared to negative control." (PMID 31145753, 2019). "Paired t tests showed that SDC1 levels in ascites (81.82 ± 16.5 ng/mL) were significantly higher (p < 0.0001) than in plasma (10.37 ± 2.4 ng/mL), suggesting that SDC1 is derived from the original tumor site." (PMID 31443604, 2019). "As shown by double immunofluorescence analysis with anti-EpCAM, anti-CD44, and anti-human CD133/1 antibodies, we observed that SDC1 was accumulated in tumor cells with CSC properties." (PMID 31443604, 2019). "Given the pro- or anti-tumor functions of Th17 cells, the exact function of Th17 cells upon culturing with Sdc-1-silenced IBC cells should be studied in detail in the future." (PMID 31145753, 2019). "The tumor epithelium of the primary ILC showed the identical overall Sdc1 expression, in 90% of them, but the intensity distribution was slightly different, and it most frequently showed a moderate expression in 56.7% and a strong expression in 26.7%." (PMID 30151336, 2018). "The basal syndecan-1 level is also crucial for understanding the progression of malignant transformation, tumor metastasis, and advanced or disseminated cancer stages." (PMID 30321230, 2018). "We have recently reported that blocking syndecan-1 activity via the specific antibody OC-46F2 leads to an anti-tumor effect by inhibiting vascular maturation and tumor growth in experimental models of human melanoma and ovarian carcinoma." (PMID 30619269, 2018). "Syndecan-1 ectodomains derived from tumor cells have been reported to exhibit opposite effects on osteoclastogenesis." (PMID 30389911, 2018). "It has been demonstrated that co-localization of syndecan-1 and integrin as well as their interactions is crucial to triggering downstream signal cascades regulating angiogenesis and tumor metastasis." (PMID 30135409, 2018). "The Sdc1 expression in the stroma of metastases positively correlated with the number of tumor foci (P = 0.022) in the primary tumor and negatively correlated with the PR expression (P = 0.032) in the primary tumor." (PMID 30151336, 2018). "After tail vein injection of tumor cells - an inoculation method that bypasses the early stages (local invasion, intravasation) of metastatic spread - host Sdc1-dependent differences in metastatic efficiency were maintained." (PMID 29976229, 2018). "Since exosomes participate in tumor cell-stroma interactions and exosomes have been shown to prepare the pre-metastatic niche, it is conceivable that host Sdc1 stimulates metastasis by modulating exosome production or loading." (PMID 29976229, 2018). "It has been revealed in vitro that purified syndecan-1 ectodomain inhibits the growth of S115 tumor cells, an epithelial-derived tumor-cell line." (PMID 30135409, 2018). "The difference in metastatic efficiency was maintained when the tumor cells were injected into the tail vein, suggesting that host Sdc1 exerts its effect during later stages of the metastatic cascade." (PMID 29976229, 2018).